Y_RNA (Y RNA )
Gene: Miscellaneous RNA gene on chromosome 3 (101,458,530 to 101,458,626, forward strand). Ensembl gene ENSG00000201554.
Homologues: Orthologues: chimpanzee Y_RNA (99% identical), macaque Y_RNA (96% identical). Paralogues in human: RNY3 (85% identical), Y_RNA (84% identical), Y_RNA (82% identical), RNY3P1 (81% identical), RNY3P14 (81% identical), Y_RNA (81% identical), Y_RNA (80% identical), RNY3P16 (79% identical), RNY3P9 (79% identical), Y_RNA (79% identical), Y_RNA (78% identical), RNY3P11 (77% identical), and 86 more.